SACK1F (scaffolding CK1 anchoring protein F)
Synonyms: FAM83F
Tractability: Antibody: UniProt places it where antibodies can reach, with high confidence; its Gene Ontology location is reachable by antibodies, with medium confidence. PROTAC: ubiquitination databases record sites on it.
Gene: Protein-coding gene on chromosome 22 (39,994,954 to 40,043,534, forward strand). Ensembl gene ENSG00000133477.
Subcellular location: Cell membrane
Subcellular location (Human Protein Atlas): Mitochondria; Nucleoplasm
Gene Ontology:
Molecular function: protein binding; protein kinase binding
Biological process: signal transduction
Cellular component: plasma membrane
Genetic constraint (gnomAD): Loss-of-function variants: 45 observed, 37.22 expected, observed/expected ratio (o/e) 1.21, 90% interval 0.95 to 1.55. The upper end of that interval is the gene's LOEUF score, 1.55, which puts it in group 6 of 6, group 1 being the genes least tolerant of losing a copy. Missense variants: 617 observed, 620.49 expected, observed/expected ratio (o/e) 0.99, 90% interval 0.93 to 1.06. Synonymous variants: 306 observed, 271.33 expected, observed/expected ratio (o/e) 1.13, 90% interval 1.03 to 1.24.
Homologues: Orthologues: chimpanzee FAM83F (97% identical), macaque FAM83F (97% identical), dog FAM83F (84% identical), pig FAM83F (82% identical), mouse Fam83f (80% identical), rat Fam83f (80% identical), guinea pig FAM83F (80% identical), rabbit FAM83F (51% identical), tropical clawed frog fam83f (45% identical), zebrafish fam83fa (36% identical), zebrafish fam83fb (31% identical), zebrafish fam83e (22% identical). Paralogues in human: SACK1G (35% identical), SACK1E (27% identical), SACK1H (26% identical), SACK1B (26% identical), SACK1D (25% identical), SACK1C (24% identical), SACK1A (23% identical).
Diseases named in the same sentence as SACK1F in open-access papers:
SACK1F is named in the same sentence as 23 diseases in open-access papers, as found by Europe PMC text mining. Sharing a sentence is not in itself a finding about the gene and the disease.
SACK1F shares sentences with these, for which no sentence is quoted: cancer (13 papers); tumor (9); esophageal squamous cell carcinoma (5); lung adenocarcinoma (5); glioma (4); papillary thyroid cancer (4); breast carcinoma (2); colorectal cancer (2); esophageal cancer (2); goiter (2); lung carcinoma (2); thyroid cancer (2); thyroid neoplasm (2); cervical cancer (1); gastric cancer (1); hepatocellular carcinoma (1); Large Cell Lung Carcinoma (1); mammary adenocarcinoma (1); osteoarthritis (1); osteosarcoma (1); ovarian carcinoma (1); thyroid (1); thyroid papillary carcinoma (1).